CCL18 (C-C motif chemokine ligand 18)
Diseases named in the same sentence as CCL18 in open-access papers (continued):
Sharing a sentence is not in itself a finding about the gene and the disease.
pulmonary fibrosis (continued). "Statistical analysis revealed an association of SSc-IgG induced high IL-8 concentrations with an early disease stage and of high CCL18 concentrations with lung fibrosis onset and vascular complications in the respective IgG donors." (PMID 24612997, 2014). "Monocytes of SSc patients and patients with pulmonary fibrosis are known to express more CCL18 than those of healthy donors." (PMID 24612997, 2014). "CCL18 is a chemokine produced and released by tumor-associated macrophages (TAM) in the microenvironment of cancer cells and pulmonary fibrosis." (PMID 23349697, 2013). "CC-chemokine ligand 18 (CCL18) is mainly expressed by alternatively activated macrophages and DCs and plays an important role in lung fibrosis, arthritis and other diseases." (PMID 22848587, 2012). "CCL18 has been reported to be an indicator of pulmonary fibrosis since BAL cells of sarcoidosis patients with X-ray stage IV produce higher levels of CCL18 compared to a lower X-ray stage." (PMID 20813038, 2010). "CCL18 is a chemotactic factor that attracts lymphocytes and it is produced by alternatively activated macrophages that contribute to inflammatory diseases, lung fibrosis, and scleroderma." (PMID 39526504, 2024). "Biomarkers previously associated with pathobiology and/or progression in pulmonary fibrosis were selected to reflect cellular senescence (telomere length), pulmonary epithelium (SP-D, RAGE), myeloid activation (CXCL13, YKL40, CCL18, OPN) and fibroblast activation (POSTN, COMP, PROC3)." (PMID 38753183, 2024). "The upregulation of CCL-8 and CCL-18 during the Th2/M2 shift may also contribute to pulmonary fibrosis and collagen production." (PMID 39281278, 2024). "Thus, CCL18 induces pulmonary fibrosis by stimulating alveolar fibroblasts to produce collagen, and CCL18 levels in blood plasma are a marker of disease activity." (PMID 35204398, 2022). "In sarcoidosis, increased CCL18 was associated with sarcoidosis-associated pulmonary fibrosis but not with other phenotypes of pulmonary disease." (PMID 36148463, 2022). "The chemokine CCL18 was also suggested to promote pulmonary fibrosis." (PMID 34769080, 2021). "Furthermore, it was demonstrated that alveolar macrophages from patients with pulmonary fibrosis show an alternatively activated phenotype, which up-regulates the production of collagen by lung fibroblasts through the production of CCL18." (PMID 32575869, 2020). "CCL18 is a factor involved in the development of pulmonary fibrosis." (PMID 33114763, 2020). "CCL18 is abundantly produced by alternatively activated macrophages in patients with idiopathic pulmonary fibrosis and its concentrations reflect the fibrotic lung activity in patients with idiopathic interstitial pneumonias, systemic sclerosis and idiopathic pulmonary fibrosis." (PMID 28957436, 2017). "In addition, serum CCL18 has been described to be raised in patients with lung fibrosis, scleroderma, inflammatory diseases such as rheumatoid arthritis, acute lymphoblastic leukaemia and gastric malignancies." (PMID 27686838, 2016). "Recently we could demonstrate that CCL18 influences survival of patients in idiopathic pulmonary fibrosis (IPF)." (PMID 22848587, 2012). "CCL18, which is constantly present in the serum of healthy subjects, has no counterpart in rodents and its serum level is increased in several benign and malign diseases like lung fibrosis, atopic dermatitis, Gaucher disease, and leukemia." (PMID 22848587, 2012). "Additionally, the levels of chemokines such as C-X-C motif chemokine ligand 10 (CXCL10) and chemokine (C-C motif) ligand 18 (CCL18) were elevated in the plasma and serum of post-COVID patients with pulmonary fibrosis, suggesting their involvement in chronic inflammation and fibrotic remodeling." (PMID 40872813, 2025).
pulmonary fibrosis (continued). "Pulmonary and activation-regulated chemokine (PARC)/CCL18 is a significant, primarily indirect, modulator of fibrosis and is elevated in association with various fibrotic lung diseases, including scleroderma, hypersensitivity pneumonitis, idiopathic pulmonary fibrosis, asthma, and sarcoidosis." (PMID 40136649, 2025). "That led us to the hypothesis that serum concentrations of CCL18 or their fluctuations during therapy could be also a potential marker for predicting RILT, as radiation pneumonitis and the ensuing pulmonary fibrosis is associated with a fibrotic remodeling of lung tissue." (PMID 28957436, 2017). "Third, high CCL18 concentrations were associated with vascular complications, including digital ulcers, PAH and renal crisis, and correlated negatively with the time since lung fibrosis onset, suggesting that the profibrotic activity of the Aabs is higher at the beginning of lung fibrosis." (PMID 24612997, 2014). "In patients with pulmonary fibrosis, increased levels of CXCL9, CXCL10, CCL18, CTO, and CA15.3 are accompanied by elevated SP-D, a component of lung surfactant and a pattern-recognition molecule produced by alveolar type II cells and Clara cells." (PMID 37445972, 2023). "CCL18 upregulation has been reported in a number of diseases, including HIV infection, atherosclerosis, pulmonary fibrosis, T2D, and in various cancers like breast, cervical, lung, and ovarian." (PMID 37046242, 2023). "CCL18 has been reported to be elevated in the serum and BALF in patients with lung fibrosis, which we also confirm in this study." (PMID 33650774, 2021). "CCL18 can also activate CCR6 on lung fibroblasts, which is important in the development of pulmonary fibrosis." (PMID 33114763, 2020). "CC chemokine ligand 18 (CCL18) produced by M2 macrophages stimulates collagen production in fibroblasts and is elevated in patients with lung fibrosis as well as in systemic sclerosis." (PMID 31791379, 2019). "Several proteins, including NADPH oxidase 4, Toll-like receptor 3, CCL18, matrix metalloproteinase-7, and interleukin-8, besides TGF-β, are widely accepted as key players in pulmonary fibrosis." (PMID 26415510, 2015). "A group of eight proteins has recently been propose as disease progression serum markers in Idiopathic Pulmonary Fibrosis (IPF): KL-6, surfactant protein A, and MMP-7, CCL-18, S100A12, IL-8, ICAM-1 and VCAM-1." (PMID 24216293, 2013). "Correlation analysis of CCL18 concentrations in supernatants with clinical features of SSc-IgG donors revealed a negative correlation with the time since lung fibrosis onset." (PMID 24612997, 2014). "However, although these results point to an important role of CCL18 in lung fibrosis, no information is available on the receptor responsible for its pro-fibrotic properties." (PMID 38334630, 2024). "Importantly, our finding that CCL18 is produced by type 2 stimulated human lung macrophages may be clinically relevant, since this chemokine is elevated in serum and BALF of idiopathic pulmonary fibrosis (IPF) where is has been identified as an important biomarker to predict mortality." (PMID 41159038, 2025).
ovarian carcinoma (36 papers, 2011 to 2025). A malignant neoplasm originating from the surface ovarian epithelium. "The levels of CCL18 in cancer tissue are related to metastasis and the shorter overall survival of patients with ovarian cancer, which seems to be associated with the increase in the mTOR Complex 2 (mTORC2) signaling pathway." (PMID 32774171, 2020). "CCL18 levels in tumor tissue are associated with metastatic spread and a shorter survival in ovarian cancer patients, which appears to involve an increase in mTORC2 signaling." (PMID 29141914, 2018). "CCL18 exerts distinct effects in various cancer types, demonstrating its ability to enhance the proliferation of specific malignancies, such as ovarian cancer and osteosarcoma." (PMID 38511143, 2024). "A notable feedback loop involving CCL18 in ovarian cancer has been shown to increase metastasis through a cascade beginning with CCL18-induced ZEB1 upregulation in cancer cells, which in turn leads to increased secretion of M-CSF." (PMID 39286635, 2024). "Chemotactic assays in vitro suggested that high level of CCL1 and CCL18 in the TME of ovarian cancer contributed to the increased infiltration of CD4+CCR8+ Tregs into tumor tissues." (PMID 37950246, 2023). "The CCL18 promoted the development of ovarian cancer through mTORC2 pathway and proline-rich tyrosine kinase 2 signaling pathway." (PMID 35609322, 2022). "CCL18 plays the role of immunosuppression in non-small cell lung cancer, oral squamous cell carcinoma, and ovarian cancer; while plays the role of protection gastric cancer." (PMID 35609322, 2022). "Previous studies have demonstrated a strong correlation between CCL18 expression and various malignancies, such as ovarian cancer, gastric cancer." (PMID 35059433, 2021). "CCL18 which endorses EMT in ovarian cancer cells showed a positive correlation with metastasis in ovarian cancer patients and further triggered EMT in the colon and hepatocellular carcinoma." (PMID 34220337, 2021). "mTOR activation via CCL18 leads to cell migration in tumors such as endometrial cancer, ovarian cancer, and oral squamous cell carcinoma." (PMID 33114763, 2020). "Pyk2 was also shown to be significantly overexpressed and a prognostic factor in ovarian cancer, and interaction of Pyk2 with CCL18 promoted ovarian cancer cell migration." (PMID 29738483, 2018). "CCL18 has also been linked to pancreatic carcinoma, where it promotes EMT and cancer cell invasion, processes that are also instrumental in ovarian cancer spread." (PMID 29141914, 2018). "In pancreatic cancer, CAF-induced IL6 secretion promotes cancer cell migration and CAF-secreted CCL18 has been shown to promote tumour invasion in breast and ovarian cancer." (PMID 28987144, 2017). "CCL18, which induces EMT in ovarian cancer cells in vitro, is also associated with high tumor grade and metastasis in patients with ovarian cancer." (PMID 28599100, 2017). "CCL18 and ascites signaling was examined in ovarian cancer cells utilizing siRNA and exogenous gene expression." (PMID 27613122, 2016). "CCL18 was identified as one of the soluble factors responsible for ascites-induced ovarian cancer cell migration through activation of Pyk2." (PMID 27613122, 2016). "The chemokine CCL18, here described as candidate ovarian cancer serum biomarker, was also considered as a urine biomarker for bladder cancer detection." (PMID 23401773, 2013). "A proteomics approach identified elevated serum CCL18 as correlated with ovarian cancer, and this finding was validated using ELISA in 535 samples." (PMID 22629457, 2012). "In combination with CXCL1, CCL18 monitoring outperformed CA125 as a circulating ovarian cancer biomarker." (PMID 22629457, 2012). "In fact, in a study of 51 patients with epithelial ovarian cancer, 27 patients with benign ovarian lesions and 29 healthy volunteers, serum CCL18 gave a sensitivity of 84.3% and a specificity of 91.1%." (PMID 22162712, 2011).
ovarian carcinoma (continued). "Other chemokines potentially involved in cancer progression include CCL18, which promoted ovarian cancer migration, CCL20, which promoted both metastasis and chemotherapy resistance, and CXCL8 (IL-8), which may contribute to peritoneal metastasis." (PMID 40689422, 2025). "CCL18 has been shown to promote immunosuppressive states and progression in esophageal squamous cell carcinoma, multiple myeloma, osteosarcoma, ovarian cancer, and renal cell carcinoma." (PMID 38511143, 2024). "Therefore, we believe that the high expression of CCL1 and CCL18 in ovarian cancer TME is an important factor in the increase of CD4+CCR8+ Tregs infiltration into tumor tissues." (PMID 37950246, 2023). "Furthermore, TAMs preferentially express cytokines and growth factors, such as CCL18, that promote tumor progression, growth and recurrence in ovarian cancer." (PMID 32774171, 2020). "Previous study reported that circulating CXCL1 combining CCL18 could be as tumor markers for the differential diagnosis between ovarian cancer and benign ovarian masses." (PMID 31998654, 2019). "Finally in the ovarian cancer cell line Skov3, CCL18 ectopic expression endows tumor cells with enhanced migratory and invasive properties in vitro (although the authors do not investigate the expression of any marker or transcription factor linked to EMT)." (PMID 28599100, 2017). "CCL18 enhances proliferation and metastasis of ovarian cancer cell lines." (PMID 27409174, 2016). "This is consistent with previous data showing high levels of CCL18 in ovarian cancer patients." (PMID 27613122, 2016). "Furthermore, it was shown that the serum level of CCL18 was elevated in epithelial ovarian cancer patients." (PMID 22162712, 2011). "However, studies on patients’ prognosis have shown that an increased expression of CCL18 in tumors such as esophageal squamous cell carcinoma, glioma, oral squamous cell carcinoma, ovarian cancer, pancreatic cancer, prostate cancer, and urothelial cancer is associated with a worse prognosis." (PMID 33114763, 2020). "Our data show that bTAM preferentially express growth factors and cytokines known to promote ovarian cancer growth, progression and relapse, such as CCL18, but also factors, which have previously not been implicated in ovarian cancer progression, e.g. KITLG and complement factors." (PMID 29141914, 2018). "Several studies have confirmed this observation - they found sensitivity to be greater than in either marker used alone: MMP-7, CCL18 (CC chemokine 18), CCL11 (CC chemokine 11) and CA125 in ovarian cancer (SE in the early stages 94.4%)." (PMID 28662671, 2017). "In this study, we showed that EVs from ovarian cancer cells upregulated genes related to the inflammatory response, including immune cell–attracting cytokines (CCL2, CCL3/L1, CCL15, CCL18, and CCL20), interleukins (IL1B and IL32), and cell–cell adhesion transcripts (VCAM1 and ICAM1)." (PMID 40689422, 2025). "In ascitic fluid from ovarian cancer patients CCL18, an attractant for Th2 cells was identified, but this chemokine was not produced by ovarian carcinoma cell lines in vitro." (PMID 30245686, 2018). "Although elevated CCL18 in body fluids was reported in patients with lung cancer, bladder cancer, and ovarian cancer, the origin of CCL18 was not determined." (PMID 26919103, 2016). "A previous study has shown that levels of CCL18 in ascites from patients with OC were significantly higher compared to those with none ovarian carcinomas." (PMID 27613122, 2016). "CCL18 is expressed at higher levels in OC ascites compared to none ovarian carcinomas." (PMID 27613122, 2016). "It was determined that CCL18 and CXCL1 had a high sensitivity for ovarian cancer diagnosis, but the specificity was not satisfactory; however, C1D, TM4SF1, TIZ, and FXR1 had a high specificity compared with a combination of CCL18 and CXCL1." (PMID 33672007, 2021).
gastric cancer (23 papers, 2010 to 2025). A primary or metastatic malignant neoplasm involving the stomach. "Although usually associated with poor prognosis in cancer, CCL18 expression in tumor sample of gastric cancer was found to predict prolonged survival." (PMID 33918621, 2021). "In gastric cancer, CCL18 overexpression has been reported to be associated with a better survival in patients." (PMID 25197632, 2014). "This was underscored by the finding of high levels of expression of CCL18 by tumor-associated macrophages in glioma and ovarian and gastric cancer." (PMID 22162712, 2011). "While iNOS contributes to development of gastric cancer, a high level of the chemokine CCL18 in gastric tumors is associated with prolonged survival of gastric cancer patients." (PMID 21124899, 2010). "Overlap analysis with genes that co-expressing in 381 gastric cancer tissues and 37 gastric cells demonstrates that various immune related genes such as CCL18, TLR8, C3AR1, CYSLTR2 and CD86 are positively correlated with CD163." (PMID 29152078, 2017). "High CCL18 expression is correlated with prolonged patient survival in gastric cancer and colorectal cancer." (PMID 26919103, 2016). "Increased CCL18 is an independent favorable prognostic biomarker in patients with colorectal cancer and gastric cancer." (PMID 26919103, 2016). "In this study, we found that CCL18 markedly increased in gastric cancer group compared to control group." (PMID 23697837, 2013). "This disparity in PITPNM3 expression between breast and gastric cancers indicates that the two malignancies may respond differently to CCL18 and explains their distinct clinical outcomes." (PMID 26919103, 2016). "In opposition to gastric cancer, CCL18 could promote the tumor malignant progression of breast cancer, ovarian cancer, bladder cancer, pancreatic cancer, and skin diseases, and its upregulation could predict poor prognosis in these cancers." (PMID 25197632, 2014). "In the comparison of metabolite interference group and M2 group marker proteins in gastric cancer cells, there were significant differences in CCL17, CCL18 and CXCL13." (PMID 39991579, 2025). "The results denoted that the levels of CCL18 and CXCL5 in 5-FU-sensitive and 5-FU-resistant gastric cancer cells were below the detection limit of the assay and recorded as zero." (PMID 36151545, 2022). "In the current study, we found that the serum levels of CCL2, CCL18, and VEGF markedly increased in gastric cancer group compared to control group." (PMID 23697837, 2013). "The aim of this study was to investigate the relationship between the preoperative serum levels of CCL2, CCL18, and VEGF, and the clinicopathological factors in patients with gastric cancer." (PMID 23697837, 2013). "The serum values of CCL2, CCL18, and VEGF in gastric cancers were 25.05 ± 1.22 (pg/ml), 115.94 ± 22.56 (pg/ml), and 132.92 ± 10.50 (pg/ml), respectively." (PMID 23697837, 2013). "The preoperative serum levels of CCL2, CCL18 and VEGF in gastric cancer patients were significantly higher than that of controls (P <0.001, P <0.001, and P <0.001, respectively)." (PMID 23697837, 2013). "CCL18+TGFBI represents a good discriminator for kidney, pancreatic and stomach cancer, which are up-regulated by at least 2-fold in cancer tissues." (PMID 21060876, 2010). "Additionally, miR-484 has been observed to target CC chemokine ligand 18 (CCL-18) through the PI3K/AKT signaling pathway, thereby inducing G1 phase cell cycle arrest, inhibiting cell proliferation, and promoting apoptosis of gastric cancer cells." (PMID 37628891, 2023). "However, an increase in Slug expression can occur by the activation by CCL18 of the ERK MAPK→NF-κB cascade, which was demonstrated on MGC-803 gastric cancer cells." (PMID 33114763, 2020). "Thus, we measured the concentration of CCL2, CCL18, and VEGF in a series of 60 serum samples from gastric cancer." (PMID 23697837, 2013).
gastric cancer (continued). "Moreover, CCL18 does not affect the proliferation of gastric cancer and pancreatic ductal adenocarcinoma cells." (PMID 33114763, 2020). "As shown, CCL18 did not affect the proliferation of BxPC-3 and PANC-1 pancreatic ductal adenocarcinoma cells, MGC-803 gastric cancer cells and GES-1 gastric epithelial cells." (PMID 35955670, 2022).
idiopathic pulmonary fibrosis (22 papers, 2012 to 2025). Idiopathic pulmonary fibrosis (IPF) is a nonneoplastic pulmonary disease that is characterized by the formation of scar tissue within the lungs in the absence of any known cause. "In idiopathic pulmonary fibrosis (IPF), one of the most common types of interstitial lung disease, CCL18 levels correlated with severity of fibrosis." (PMID 30245686, 2018). "In patients with idiopathic pulmonary fibrosis (IPF), the alveolar epithelium lining fluid contains mediators that alter fibroblast activity, such as CCL18, LPA, TGF-b and PDGF." (PMID 27769060, 2016).